GBP1 (guanylate binding protein 1)
Diseases named in the same sentence as GBP1 in open-access papers (continued):
Sharing a sentence is not in itself a finding about the gene and the disease.
viral infection (26 papers, 2011 to 2026). "It has been demonstrated that GBP1 possesses antiviral functions, in turn, viral infection can affect its expression levels." (PMID 36918936, 2023). "In the earlier studies, GBP1 was mainly regarded as a interferon/cytokine inducer or virus infection responder in hostcells." (PMID 31998647, 2019). "Human guanylate-binding protein 1 (hGBP1) is an interferon-inducible protein involved in the host immune response against viral infection." (PMID 23405236, 2013). "Our results uncover a previously unknown antiviral mechanism of GBP1, offering a promising target for the prevention of viral infections." (PMID 42012181, 2026). "For example, overexpression of VP1 inhibits type I IFN production and response via interacting with host proteins; hepatitis C virus obviously suppresses the expression of ISG such as GBP1 which in turn interferes with virus infection by interacting with the viral protein NS5B." (PMID 35937300, 2022). "The induced transcriptions of multiple GBP1 orthologs by the engineered S. cerevisiae expressing gcH2A-4 and gcH2A-11 suggest the possible protective effect of gcH2A-4 and gcH2A-11 in the grass carp against bacterial or viral infections." (PMID 35898515, 2022). "We also found the upregulation of GBP1 protein upon virus infection." (PMID 35663470, 2022). "Notably, GBP1 has been reported to restrict viral infection, especially against RNA viruses." (PMID 40006915, 2025). "Overexpression of IFITM3 and other ISGs, such as IFN-induced guanylate-binding protein 1 (GBP1) and stimulator of IFN genes (STING), has been reported to induce autophagy during virus infection." (PMID 40681213, 2025). "It has been reported that interferon can significantly trigger the production of many interferon-induced genes (IFIT1, IFITM3, MX-1, OASL, ISG15, PKR, GBP1, Viperin, BST2, IRF-1, and CXCL10), which play key roles in the resistance to viral infection." (PMID 36337195, 2022). "The present study demonstrated that porcine GBP1 is an effective anti-PRRSV host factor, and overexpression of GBP1 significantly inhibited PRRSV infection, while knockdown of endogenous GBP1 promoted viral infection." (PMID 35804432, 2022). "The initial defense and adaptive immune responses against viral infection are performed by type I IFNs (IFN-α/β) such as RTP4, GBP1, OAS1, IFI27, and IF44L." (PMID 31665046, 2019). "The antiviral-ISG, including GBP1, IFI44, IFIH1, IFIT1, MX1, and LY6E, were the most common group of up-regulated genes after influenza infection, yellow fever vaccination, and during febrile episodes of dengue hemorrhagic fever." (PMID 24069471, 2013). "This aligns with Kim and others who found that GBP1 plays a critical role in regulating inflammation during viral infections, although their study focused on non-pregnant populations." (PMID 40332395, 2025). "Additionally, upregulated expression of antiviral genes such as GBP1, GBP2 and CCL2 was also observed, which is closely related to the inflammatory response elicited by viral infection." (PMID 39872814, 2024). "Meanwhile, we found that IFNs could significantly trigger the production of a variety of IFN-induced genes (IFIT1, IFITM3, Mx-1, OASL, ISG15, PKR, GBP1, Viperin, BST2, IRF-1, and CXCL10) and MHC molecules, which play key roles in resistance to virus infection." (PMID 32655518, 2020). "In order to figure out whether mRNAs and miRNAs in the ceRNA network have effects on viral infection, we investigated the effect of selected six representative mRNAs (CMPK2, ISG15, PARP10, SAMD9, GBP1, and RIG-I) involved in the ceRNA network upon HTNV infection." (PMID 32232013, 2020). "Furthermore, GBP1 reduces radioresistance of two human oral and liver cancer cell lines and correlates with better prognosis in melanoma but with poorer prognosis in human glioblastoma, (iii) GBP4 inhibits innate responses to viral infection but lacks known tumor related functions to date." (PMID 32265897, 2020).
viral infection (continued). "In particular, 8 genes (Mx1, EPSTI1, XAF1, IFI44L, GBP1, SAMD9, SAMD9L, and CMPK2) were expressed in the highly resistant cell lines HPAF-II and Hs766T but not the highly permissive cell lines MIA PaCa-2 and Capan-1 in the absence of virus infection." (PMID 27533247, 2016).
colorectal cancer (22 papers, 2012 to 2025). A primary or metastatic malignant neoplasm that affects the colon or rectum. "GBP1 has been reported to be associated with better prognosis in colorectal cancer, liver cancer, epithelial ovarian cancer, triple negative breast cancer, cutaneous melanoma and other cancers." (PMID 38167153, 2024). "The anti-proliferative activity of GBP-1 has been associated with decreased progression in some cancer types, such as breast and colorectal cancer." (PMID 39114443, 2024). "GBP1 expression has been associated with a prognostically positive Th1 immune response in colorectal cancer." (PMID 32093058, 2020). "Our experimental results are supported by clinical findings in colorectal cancer patients where increased GBP-1 expression from endothelial cells was associated with a reduction in angiogenesis." (PMID 23217187, 2012). "Lastly, the roles of guanylate‐binding protein 1 (GBP1) in cancer are seemingly context‐dependent, since its upregulation was associated with decreased progression in breast and colorectal cancer, but increased progression, metastasis, and resistance in ovarian cancer and glioblastoma." (PMID 34894177, 2022). "Interestingly, ITGA2 was a senescence associated inflammatory factor in colorectal cancer, while GBP1 was an interferon-responsive gene in innate immunity." (PMID 35169119, 2022). "GBP1 upregulation is reported to be associated with decreased disease progression and better overall survival in patients with breast and colorectal cancer, while it is connected with increased disease progression, metastasis, and treatment resistance in ovarian cancer and glioblastoma." (PMID 34759950, 2021). "Similar complexity has been found in colorectal cancer, where loss of GBP1-mediated apoptotic responsiveness to interferon signaling is associated with co-regulation of genes involved in immunosuppression, which facilitates disease progression and portends worsened prognosis." (PMID 32117203, 2019). "Interestingly, up-regulation of GBP-1 in humans also has been associated with a highly significant (p<0.001) increase in five-year survival rate in colorectal cancer patients." (PMID 23226526, 2012). "GBP-1, which is expressed in response to interferon-γ, is considered to be an activation marker during inflammatory diseases, and up-regulation of GBP-1 in humans has been associated with a highly significant, increased five-year survival rate in colorectal cancer patients." (PMID 23226526, 2012). "In colorectal cancer, GBP1 promotes immune activation by recruiting effector cells, including macrophages, dendritic cells, and T lymphocytes, to suppress tumors." (PMID 40564939, 2025). "Studies have found that GBP1 is also widely expressed in various tumors, such as colorectal cancer and prostatic cancer." (PMID 38167153, 2024). "GBP1 functions as a tumor suppressor in colorectal cancer, and in contrast, can protect prostate carcinoma cells from IFNγ-mediated apoptosis." (PMID 36187937, 2022). "Human GBP-1 (hGBP-1) expression is correlated with better prognosis in breast and colorectal cancers." (PMID 34830789, 2021). "One report showed that GBP1 is downregulated and acts as a tumor suppressor in colorectal cancer cells." (PMID 26848767, 2016). "GBP1 acts as a tumor suppressor in colorectal cancer cells, and also plays a role in chronic active EBV infection and interacts with HCV NS5B." (PMID 25207815, 2014). "In this context, GBP-1 has been identified as a potent anti-angiogenic mediator in colorectal carcinoma, where a positive correlation was found between a high GBP-1 expression from tumor endothelial cells and reduced angiogenesis within the tumor." (PMID 23217187, 2012). "Conversely, in colorectal cancer, GBP1 suppresses tumor growth, reducing proliferation and improving overall survival, possibly by enhancing immune recognition of tumor cells—a role tied to its predominant expression in gastrointestinal tissues and interferon-driven immune activation." (PMID 40564939, 2025).
colorectal cancer (continued). "On the one hand, studies have found that the anti-tumor effect of GBP1 is reflected in colorectal cancer, liver cancer, epithelial ovarian cancer, high-grade serous ovarian cancer and other cancers, and high expression of GBP1 is associated with better survival prognosis in these cancer patients." (PMID 38167153, 2024). "GBP1, considered a tumor-repressor gene, was found to be downregulated in colorectal cancer." (PMID 35631574, 2022). "GBP-1 inhibits epithelial cell and colorectal cancer cell proliferation." (PMID 34830789, 2021). "In colorectal cancer, GBP1 can inhibit tumor cell proliferation." (PMID 33552086, 2020). "Recent data indicated that the GBP1-mediated anti-proliferative effects on human colorectal cancer cells DLD1 are mediated by a specific amino acid sequence at the N-terminus of the GBP1-α9-helix, which interacts with the DNA-binding domain of the transcription factor TEA Domain protein (TEAD)." (PMID 32093058, 2020). "Study found that GBP1 acts specifically as a tumor suppressor in colorectal carcinoma and the reduction of GBP1 expression might imply cancer evasion from the IFN-γ-dominated Th1 immune response." (PMID 32269280, 2020). "GBP1’s tumor-suppressive role in colorectal cancer contrasts with its oncogenic effects in glioblastoma, risking adverse outcomes with broad inhibition—suppressing it might shrink gliomas but spur colorectal tumors, a complexity necessitating tumor-specific precision." (PMID 40564939, 2025). "Recently, it was shown that GBP1 and GBP4 are IFNG-dependent and were directly co-expressed with CD8A in colorectal cancer." (PMID 34487971, 2021). "To translate this finding to colorectal cancer cells, we used DLD1 cells as a model system because they lack endogenous GBP-1 expression." (PMID 30120107, 2018). "Why do GBP1 and GBP2 exhibit opposing roles across cancers—e.g., tumor suppression in colorectal cancer versus oncogenicity in glioblastoma—and can machine learning, multi-omics analysis, or systems biology predict these patterns from genomic, proteomic, or transcriptomic data." (PMID 40564939, 2025). "Based on these findings, Naschberger and colleagues could attribute GBP-1, resulting from IFN-γ upregulation in colorectal carcinoma (CRC), to an IFN-γ-dominated Th1-like immune reaction possessing potential angiostatic/antiangiogenic activity." (PMID 34249014, 2021). "The large GTPase human guanylate-binding protein 1 (GBP-1) is highly induced by IFN-γ and indicates activation of cells by this cytokine in diseased tissues in inflammatory bowel diseases, colorectal carcinoma (CRC), and others." (PMID 30120107, 2018).
ovarian carcinoma (20 papers, 2016 to 2025). A malignant neoplasm originating from the surface ovarian epithelium. "In ovarian cancer, GBP1 protects cells from paclitaxel by associating with beta-tubulin and indoleamine 2,3-dioxygenase 1 (IDO-1), enhancing survival under chemotherapeutic stress and enabling drug resistance." (PMID 40564939, 2025). "GBP1 protects ovarian cancer cells from paclitaxel by associating with beta-tubulin, altering cytoskeletal dynamics to sequester the drug within the microtubule network, and partnering with IDO-1 to reduce apoptosis—a dual shield against cell death that enhances chemotherapeutic resistance." (PMID 40564939, 2025). "The results from Kaplan-Meier analysis indicated that GBP1 could act as a risk factor for ovarian cancer and skin cutaneous melanoma, while it may serve as a protective factor for lower grade glioma, kidney renal papillary cell carcinoma, and uveal melanoma." (PMID 37796192, 2023). "High GBP1 expression inhibited tumor cell proliferation in breast and colorectal cancers, but it was strongly associated with disease progression and paclitaxel resistance in ovarian cancer and glioblastoma." (PMID 35222540, 2022). "In addition, GBP1 is linked to radiotherapy resistance in head and neck tumors and is a component of the cytoskeletal gateway of drug resistance in ovarian cancer, especially for paclitaxel, which is a common therapeutic choice for treating TNBC." (PMID 29115931, 2017). "Furthermore, GBP1 overexpression is associated with malignant features in different tumor types, such as glioblastoma, oral cancer, esophageal squamous cell cancer, ovarian cancer and lung cancer." (PMID 31998647, 2019). "GBP4 exhibits a split personality—favoring survival in ovarian cancer by supporting immune responses through immunomodulatory factors, yet worsening renal cancer outcomes by enhancing tumor resilience, echoing GBP1’s duality." (PMID 40564939, 2025). "Cytokine stimulation in tumor cells leads to the release of soluble GBP1 both in vivo and in vitro, suggesting a potential antitumor effect in ovarian cancer." (PMID 37796192, 2023). "In this report, we show for the first time that the leaderless protein GBP1 is released by IL-27- or IFN-γ-stimulated ovarian cancer cells in vitro, whereas other members of the GBP family are induced intracellularly but not secreted." (PMID 32093058, 2020). "Preliminary, we verified GBP1 expression in the TCGA-OV RNA-seq dataset containing 373 human ovarian cancers." (PMID 32093058, 2020). "This figure was increased to 80% of ovarian cancer patients after treatment with paclitaxel or docetaxel and follow-up study found GBP1 expression was a significant correlate of decreased progression-free survival." (PMID 32117203, 2019). "This trend was first noted in profiling of human ovarian cancer cell lines, which found that high GBP1 expression strongly correlated with paclitaxel resistance and that its knock-out restored treatment sensitivity." (PMID 32117203, 2019). "The network based approach identified two 7-gene functional interaction modules (31: DCLRE1A, EXO1, KIAA0101, KIN, PCNA, POLD3, POLD2; 35: DKK3, FABP3, IRF1, AIM2, GBP1, GBP2, IRF2) that are associated with prognosis of ovarian cancer patients." (PMID 27806724, 2016). "GBP1 expression is a significant prognostic factor of PFS in patients with ovarian cancer." (PMID 40018406, 2025). "Similarly, ectopic expression of GBP1 in ovarian cancer cells reduces their viability by ~25% within 3 days." (PMID 37797010, 2023). "However, GBP1 expression promoted tumor progression in oral cavity squamous cell carcinoma and ovarian cancer." (PMID 35222540, 2022). "GBP1 binds to proto-oncogene serine/threonine-protein kinase pim-1 (PIM1) and causes paclitaxel resistance in ovarian cancer, implying that PIM1 might interact with GBP5 for drug resistance in OSCC." (PMID 34439200, 2021).
ovarian carcinoma (continued). "Collectively, these data prompted us to investigate whether GBP1 may accumulate in the peritoneal fluids of ovarian cancer and possibly in the sera." (PMID 32093058, 2020). "However, in oral squamous cell carcinoma and ovarian cancer, GBP1 confers tumor cells with stronger drug resistance, and its expression level is related to the poor prognosis of patients." (PMID 33552086, 2020). "Moreover, GBP1 is described as a component of the cytoskeletal gateway of drug resistance in ovarian cancer." (PMID 29115931, 2017). "Furthermore, GBP1 was shown to be upregulated in paclitaxel-resistant ovarian cancer cells and to confer moderate paclitaxel resistance." (PMID 26848767, 2016). "Furthermore, high GBP1 expression may also act as a mediator of paclitaxel resistance in human ovarian cancer cell lines and radioresistance in a variety of cancer cell lines." (PMID 35222540, 2022). "However, this activity appears to be context-dependent, as in other cancers, such as oral squamous cell carcinoma and ovarian cancer, GBP1 activity appears to anchor a complex, taxane chemotherapy resistance profile where its expression levels correlate with worsened prognosis in patients." (PMID 32117203, 2019). "Furthermore, preliminary experiments with small molecule-mediated inhibition of GBP1's association with PIM1 have demonstrated restoration of treatment sensitivity and reduction in ovarian cancer growth, showing that GBP1 is an excellent molecular target for combating TXR in tumor progression." (PMID 32117203, 2019). "Currently, although numerous molecular subtyping has been developed in ovarian cancer, such as IFNG, CD30, CXCL13, PRF1 GBP1, and ETV7 CTLA-4, they provided limited prognostic information or are not validated in the clinical samples." (PMID 36157232, 2022). "NSC756093 is a potent in vitro inhibitor of the GBP1:PIM1 interaction and this property is maintained in vivo in ovarian cancer cells resistant to taxane." (PMID 31998647, 2019). "Indeed, a 4-aza podophyllotoxin derivative was demonstrated to act as a potent in vitro inhibitor of the GBP1:PIM1 interaction, which is a property that is maintained in vivo in ovarian cancer cells resistant to paclitaxel." (PMID 29115931, 2017).